Y_RNA (Y RNA )
Gene: Miscellaneous RNA gene on chromosome 11 (108,084,913 to 108,085,014, forward strand). Ensembl gene ENSG00000200855.
Homologues: Orthologues: chimpanzee Y_RNA (98% identical), macaque Y_RNA (95% identical), guinea pig Y_RNA (91% identical). Paralogues in human: RNY3 (93% identical), Y_RNA (91% identical), RNY3P1 (90% identical), Y_RNA (90% identical), Y_RNA (89% identical), RNY3P14 (88% identical), Y_RNA (88% identical), RNY3P9 (87% identical), Y_RNA (87% identical), Y_RNA (86% identical), RNY3P16 (85% identical), Y_RNA (85% identical), and 96 more.